ZDHHC2 (zDHHC palmitoyltransferase 2)
Description:
Palmitoyltransferase that catalyzes the addition of palmitate onto various protein substrates and is involved in a variety of cellular processes. Has no stringent fatty acid selectivity and in addition to palmitate can also transfer onto target proteins myristate from tetradecanoyl-CoA and stearate from octadecanoyl-CoA (By similarity). In the nervous system, plays a role in long term synaptic potentiation by palmitoylating AKAP5 through which it regulates protein trafficking from the dendritic recycling endosomes to the plasma membrane and controls both structural and functional plasticity at excitatory synapses (By similarity). In dendrites, mediates the palmitoylation of DLG4 when synaptic activity decreases and induces synaptic clustering of DLG4 and associated AMPA-type glutamate receptors (By similarity). Also mediates the de novo and turnover palmitoylation of RGS7BP, a shuttle for Gi/o-specific GTPase-activating proteins/GAPs, promoting its localization to the plasma membrane in response to the activation of G protein-coupled receptors. Through the localization of these GTPase-activating proteins/GAPs, it also probably plays a role in G protein-coupled receptors signaling in neurons (By similarity). Also probably plays a role in cell adhesion by palmitoylating CD9 and CD151 to regulate their expression and function. Palmitoylates the endoplasmic reticulum protein CKAP4 and regulates its localization to the plasma membrane. Could also palmitoylate LCK and regulate its localization to the plasma membrane. (Microbial infection) Promotes Chikungunya virus (CHIKV) replication by mediating viral nsp1 palmitoylation.
Synonyms: ZNF372; DHHC2
Tractability: Antibody: UniProt places it where antibodies can reach, with high confidence; its Gene Ontology location is reachable by antibodies, with high confidence; UniProt predicts a signal peptide or a membrane-spanning region; the Human Protein Atlas places it where antibodies can reach. PROTAC: ubiquitination databases record sites on it; its protein half-life has been measured; a small molecule that binds it is known.
Target class: Enzyme; Transferase
Gene: Protein-coding gene on chromosome 8 (17,155,974 to 17,224,799, forward strand). Ensembl gene ENSG00000104219.
Subcellular location: Postsynaptic density; Postsynaptic recycling endosome membrane; Cell membrane; Endoplasmic reticulum membrane; Golgi apparatus membrane
Subcellular location (Human Protein Atlas): Plasma membrane
Pathways (Reactome):
Disease: Maturation of spike protein
Metabolism of proteins: Surfactant metabolism
Gene Ontology:
Molecular function: palmitoyltransferase activity; protein homodimerization activity; protein-cysteine S-palmitoyltransferase activity; protein-cysteine S-myristoyltransferase activity; protein-cysteine S-stearoyltransferase activity
Biological process: peptidyl-L-cysteine S-palmitoylation; protein localization to membrane raft; regulation of cell-cell adhesion; regulation of protein catabolic process; regulation of protein localization to plasma membrane; synapse assembly; positive regulation of AMPA glutamate receptor clustering; positive regulation of endosome to plasma membrane protein transport; positive regulation of long-term synaptic potentiation; protein localization to plasma membrane; protein localization to postsynaptic membrane; protein targeting to membrane; regulation of neuronal synaptic plasticity; synaptic vesicle maturation; regulation of postsynaptic neurotransmitter receptor diffusion trapping
Cellular component: endoplasmic reticulum; endoplasmic reticulum membrane; Golgi apparatus; Golgi membrane; plasma membrane; postsynaptic recycling endosome; postsynaptic density; postsynaptic recycling endosome membrane; glutamatergic synapse; recycling endosome membrane
Genetic constraint (gnomAD): Loss-of-function variants: 41 observed, 38.14 expected, observed/expected ratio (o/e) 1.07, 90% interval 0.84 to 1.39. The synonymous counts are far from expectation, so gnomAD's model fits this gene poorly and the ratio says little. Missense variants: 434 observed, 366.9 expected, observed/expected ratio (o/e) 1.18, 90% interval 1.09 to 1.28. Synonymous variants: 183 observed, 127.72 expected, observed/expected ratio (o/e) 1.43, 90% interval 1.27 to 1.62.
Homologues: Orthologues: chimpanzee ZDHHC2 (100% identical), macaque ZDHHC2 (98% identical), dog ZDHHC2 (96% identical), pig ZDHHC2 (96% identical), rat Zdhhc2 (95% identical), mouse Zdhhc2 (95% identical), guinea pig ZDHHC2 (85% identical), tropical clawed frog zdhhc2 (83% identical), zebrafish zdhhc2 (74% identical), rabbit ZDHHC2 (73% identical), Drosophila melanogaster CG1407 (46% identical), Caenorhabditis elegans dhhc-4 (37% identical), and 7 more. Paralogues in human: ZDHHC20 (61% identical), ZDHHC15 (52% identical), ZDHHC14 (22% identical), ZDHHC3 (20% identical), ZDHHC18 (19% identical), ZDHHC9 (19% identical), ZDHHC7 (19% identical), ZDHHC1 (18% identical), ZDHHC6 (17% identical), ZDHHC4 (14% identical), ZDHHC12 (14% identical), ZDHHC19 (14% identical), and 5 more.
Diseases named in the same sentence as ZDHHC2 in open-access papers:
ZDHHC2 is named in the same sentence as 34 diseases in open-access papers, as found by Europe PMC text mining. Sharing a sentence is not in itself a finding about the gene and the disease. The quoted sentences say what the papers report.
hepatocellular carcinoma (7 papers, 2013 to 2025). A malignant tumor that arises from hepatocytes. "ZDHHC2 is located in chromosome 8p21.3-22, where frequent loss of heterozygosity has been detected in various types of metastatic cancers, and somatic mutations of this gene were found in colorectal cancer, hepatocellular carcinoma, and nonsmall lung cancer." (PMID 23457560, 2013). "In this way, the genes selected for ChIP analysis were: PADI3, a tumour suppressor in CRC, ZDHHC2, a suppressor of metastasis in hepatocellular carcinoma and RGS4, which inhibits the growth of human breast carcinoma cells." (PMID 33801071, 2021). "In humans, aberrant ZDHHC2 expression or translocation has been described in several cancers, including acute myeloid leukemia and hepatocellular carcinoma." (PMID 32587588, 2020). "We found that neither S306 F (hepatocellular carcinoma) nor M356I (colorectal cancer) mutation within the C-terminal cytoplasmic tail of zDHHC2 affected auto-S-palmitoylation." (PMID 39800157, 2025). "The reported substrates of ZDHHC2 also includes CD9 and CD151 in HEK293 cells, Lck in T cells, and CKAP4 in hepatocellular carcinoma and interstitial cystitis." (PMID 32587588, 2020).
gastric adenocarcinoma (6 papers, 2013 to 2025). "It was reported that reduced ZDHHC2 expression is observed in gastric adenocarcinoma patients and associated with lymph node metastasis and independently predicts an unfavorable prognosis." (PMID 24995331, 2014). "In conclusion, reduced ZDHHC2 in gastric adenocarcinoma is associated with lymph node metastasis and poor prognosis of the patients." (PMID 23457560, 2013). "Reduction of ZDHHC2 expression was observed in 44.7% (211/472) of gastric adenocarcinoma patients, and was associated significantly with lymph node metastasis (p<0.001) and histological grade (p<0.001)." (PMID 23457560, 2013). "Our data suggest that reduced ZDHHC2 expression is associated with lymph node metastasis and independently predicts an unfavorable prognosis in gastric adenocarcinoma patients." (PMID 23457560, 2013). "Low expression of ZDHHC2 was observed in 44.7% (211/472) of gastric adenocarcinoma patients, and was associated significantly with lymph node metastasis (p<0.001) and histological grade (p<0.001)." (PMID 23457560, 2013). "Reduction of ZDHHC2 expression was observed in 44.7% (211/472) of gastric adenocarcinoma patients, and was associated significantly with lymph node metastasis and histological grade." (PMID 23457560, 2013). "Therefore we proposed that the reduction of ZDHHC2 expression in gastric adenocarcinoma might be caused by several different ways, including haploid insufficiency due to loss of one chromosome, mutation and epigenetic alteration." (PMID 23457560, 2013). "Studies have analyzed differences in the expression of ZDHHC2 in GC tissues and adjacent normal tissues, revealing that ZDHHC2 expression is downregulated in gastric adenocarcinoma." (PMID 40681504, 2025). "Quantitative Real-Time PCR (qRT-PCR) and immunostaining were performed to detect ZDHHC2 expression in gastric adenocarcinoma, and then the correlation between ZDHHC2 expression and clinicpathologic parameters, and patient survival was analyzed." (PMID 23457560, 2013). "Due to its proposed role in cancer, in this study, we aimed to investigate the expression pattern of ZDHHC2 in gastric adenocarcinoma, and its clinicopathological implications." (PMID 23457560, 2013). "The potential of ZDHHC2 as therapeutic targets for gastric adenocarcinoma should be further investigated." (PMID 23457560, 2013). "Cancer and DHHC enzymes are closely associated; for example, copy number variation of a chromosome region including the gene of ZDHHC11 is observed in lung and bladder cancers, and decreased expression of ZDHHC2 has been found in colorectal cancers and gastric adenocarcinoma." (PMID 30658672, 2019). "Hence, our results also proposed that ZDHHC2 was a putative tumor/metastasis suppressor in gastric adenocarcinoma, which were consistent with previous studies of ZDHHC2." (PMID 23457560, 2013). "ZDHHC2 expression pattern and its clinical significance have not yet been investigated in gastric adenocarcinoma." (PMID 35057823, 2022). "The expression pattern of ZDHHC2 and its clinical significance in gastric adenocarcinoma have not been determined to date." (PMID 23457560, 2013). "However ZDHHC2 expression pattern and its clinical significance have not yet been investigated in gastric adenocarcinoma." (PMID 23457560, 2013).
prostate carcinoma (6 papers, 2013 to 2026). A carcinoma that arises from epithelial cells of the prostate gland. "Although ZDHHC2 promotes enzalutamide resistance in prostate cancer, the underlying mechanisms remain to be elucidated, so multi‐omics analyses were performed with control and ZDHHC2 knockdown C4‐2 cell lines." (PMID 41126755, 2026). "ZDHHC2 is also associated with inhibiting the metastasis of cancer cells, and is usually missing in metastatic liver cancer, colon cancer, prostate cancer, breast cancer and non-small cell lung cancer." (PMID 36774350, 2023). "We propose that ZDHHC2‐mediated suppression of ferroptosis contributes to the development of enzalutamide resistance in prostate cancer." (PMID 41126755, 2026). "To elucidate the role of ZDHHC2 in the enzalutamide response in spontaneous prostate cancer models, we established a ZDHHC2 knockout (KO) mouse model through CRISPR/Cas‐mediated genome engineering and verified ZDHHC2 KO via PCR and western blotting." (PMID 41126755, 2026). "In summary, our study revealed a novel mechanism by which ZDHHC2 mediated S‐palmitoylation modulates ferroptosis and castration sensitivity in prostate cancer via controlling lipid peroxide production." (PMID 41126755, 2026). "Our lipidomics analysis revealed that ZDHHC2 knockdown significantly altered the lipid metabolite composition in prostate cancer cells, providing compelling evidence for the pivotal role of ZDHHC2 in mediating enzalutamide resistance through lipid metabolic reprogramming." (PMID 41126755, 2026). "Immunohistochemical (IHC) staining of a prostate cancer tissue microarray revealed a negative correlation between the protein levels of ACSL4 and ZDHHC2." (PMID 41126755, 2026).
colorectal cancer (5 papers, 2013 to 2025). A primary or metastatic malignant neoplasm that affects the colon or rectum. "ZDHHC2 (Palmitoyltransferase or Reduced Expression Associated with Metastasis Protein) has been linked to human colorectal cancers with liver metastasis." (PMID 32164540, 2020). "The mRNA level of ZDHHC2 expression was significantly reduced in primary and metastatic foci of advanced colorectal cancer." (PMID 23457560, 2013).
lymph node metastasis (4 papers, 2013 to 2023). "Reduced ZDHHC2 expression has been linked to lymph node metastasis and is an independent predictor of poor prognosis in gastric adenocarcinoma." (PMID 36018061, 2023). "Interestingly, reduced ZDHHC2 expression was associated significantly with lymph node metastasis (p<0.001) and histological grade (p<0.001)." (PMID 23457560, 2013).
psoriasis (3 papers, 2020 to 2025). An autoimmune condition characterized by red, well-delineated plaques with silvery scales that are usually on the extensor surfaces and scalp. "Our results showed that in mice Zdhhc2 deficiency was able to inhibit accumulation of immune cells in the lesioned skin during psoriasis development and very importantly the production of crucial pro-inflammatory cytokines were also dramatically decreased." (PMID 33488612, 2020). "Amelioration in psoriasis and dramatically reduced inflammation of Zdhhc2 deficient mice led us to analyze the cellular components that were affected by loss of Zdhhc2." (PMID 33488612, 2020). "To further understand the effect of Zdhhc2-deficiency on psoriasis, we performed H&E staining and flow cytometry analysis of psoriatic skin from WT and Zdhhc2−/− mice." (PMID 33488612, 2020). "ZDHHC2 deficiency attenuates pathological progression in mice by inhibiting pro-inflammatory cytokine expression in inflamed skin and leukocyte infiltration in psoriatic lesion areas, and ZDHHC2 deficiency reduces migration of pDC to the skin and other organs, which reduces psoriasis risk." (PMID 40959086, 2025). "In this study, we found that the mRNA level of Zdhhc2 was significantly elevated in mice inflamed skin upon imiquimod-induced psoriasis." (PMID 33488612, 2020). "Interestingly, Zdhhc2 deficiency mice exhibited significantly lower frequency and count of pDC than the WT mice, indicating that loss of Zdhhc2 potently inhibits the infiltration of pDC to organs, especially the skin, thereby reducing the incidence of psoriasis." (PMID 33488612, 2020). "To functionally decipher the role of Zdhhc2 in psoriasis, we applied imiquimod on the ear skin of WT controls and Zdhhc2−/− mice to induce inflammation and compare the pathological changes." (PMID 33488612, 2020). "In the present study, we found that the mRNA level of Zdhhc2 was significantly elevated in mice inflamed skin upon imiquimod-induced psoriasis which suggested that there is a potential correlation between Zdhhc2 gene and the occurrence of psoriasis." (PMID 33488612, 2020). "The functional identification of Zdhhc2 and mechanistic discoveries in our study provide an insight into possibilities of manipulating the enzymatic activity of zDHHC2 for treatment of skin inflammatory diseases such as psoriasis." (PMID 33488612, 2020). "Hence it is of great interest to determine the contribution of Zdhhc2 to pDCs mediated inflammation in different organs during psoriasis modeling." (PMID 33488612, 2020). "The functional identification of zDHHC2 and mechanistic discoveries in our study suggest that manipulating the enzymatic activity of zDHHC2 might be a potential option for treatment of psoriasis and pDCs mediated inflammatory diseases." (PMID 33488612, 2020). "Our experiments showed that pDCs an important cellular subset of inflammatory response in psoriasis require the presence of Zdhhc2 to infiltrate and to function in the skin, and the absence of Zdhhc2 notably blocked both gathering of pDCs and development of skin pathology." (PMID 33488612, 2020). "Therefore, we identified novel function of Zdhhc2 in controlling inflammatory response in psoriasis in mice and we also confirmed that crucial role of Zdhhc2 in pDCs by regulating IRF7 activity and production of the critical cytokine." (PMID 33488612, 2020). "On this basis, we performed genetic deletion of Zdhhc2 in C57BL/6 mice by CRISPR/Cas9 system, and first delineated that the knockout of Zdhhc2 in mice was sufficient to mitigate psoriasis." (PMID 33488612, 2020). "To further gain insight into the function of Zdhhc2 in psoriasis, we used CRISPR/Cas9 system by designing two sgRNAs to target Zdhhc2 in mice." (PMID 33488612, 2020). "In conclusion, our study identified the critical role of Zdhhc2 in development of psoriasis and pDC accumulation in the skin and we found that IFN-α production was completely dependent on Zdhhc2." (PMID 33488612, 2020).
renal cell carcinoma (2 papers, 2024 to 2026). "ZDHHC2 exhibits aberrant upregulation in renal cell carcinoma and plays a role in lipid production and carcinogenesis by modulating the ZDHHC2-AGK signaling axis." (PMID 39148124, 2024).
schizophrenia (2 papers, 2022 to 2023). A major psychotic disorder characterized by abnormalities in the perception or expression of reality. "A targeted study identified rare mutations within the ZDHHC2 coding sequence of Han Chinese patients suffering from schizophrenia." (PMID 36087837, 2022). "Genome-wide association analyses have identified ZDHHC2 as a candidate gene for schizophrenia as well as Parkinson’s disease." (PMID 36087837, 2022). "We chose to further study ZDHHC2 and ZDHHC5 as they have been shown to regulate activity-induced palmitoylation of synaptic proteins, as well as ZDHHC8 and ZDHHC9 as their function is disrupted in a subset of patients with schizophrenia and X-linked intellectual disability, respectively." (PMID 37039765, 2023).
autoimmune disorders (1 paper, 2022). "zDHHC2 inhibition could also be of use for the management of several autoimmune disorders involving the lymphocyte-specific protein tyrosine kinase Lck." (PMID 36087837, 2022).